TNF (tumor necrosis factor)
Diseases named in the same sentence as TNF in open-access papers (continued):
Sharing a sentence is not in itself a finding about the gene and the disease.
synovitis (continued). "IPFP area was neither associated with BMI, body fat, trunk fat, leg muscle strength and patellofemoral synovitis, nor with leptin, IL-6 and TNF-α (data not shown)." (PMID 25008048, 2014). "Although synovitis score and the expression levels of RANKL, OPG and TNF-α were similar in AIA and AIA + HFD groups, bone resorption activity was remarkably increased in AIA + HFD rabbits suggesting a greater RANKL activity or efficiency in the presence of high LDL levels." (PMID 23941259, 2013). "AIA synovitis is accompanied by a nonsignificant 6-fold local elevation of TNF-α message, but a significantly increased protein production (5-fold; peak level approximately 400 ng/mg total protein)." (PMID 15899031, 2005). "Low-level evidence suggests that TNF-α inhibitors may be effective for knee OA, but it is unclear whether the effect is stronger in patients with synovitis and there were no rigorously conducted RCTs to date." (PMID 38961031, 2024). "The absent response in IL-1β concentration and the brief TNF-α increase observed in IL-1β-induced synovitis joints differ from previous findings in the amphotericin B-induced synovitis model, which showed a sustained increase in concentration of these cytokines in synovial fluid for 9 weeks." (PMID 33980227, 2021). "Activation of nrf2 may suppress TNF-α-induced proliferation, invasion, and MMPs expression in RA-FLS by inhibiting JNK activation, indicating that nrf2 plays a protective role in relieving the severity of synovitis in RA." (PMID 33426091, 2020). "However, anti-TNFα treatment initiated at D7, not D21, significantly provided protection (Synovitis score of 1.8 ± 0.9 vs. 3.9 ± 0.3)." (PMID 31892201, 2019). "Nonetheless, if anti-TNFα therapy was initiated after multiple bleeding episodes (day 21 after three injuries), no additional benefit was achieved (Synovitis score of 3.8 ± 0.3, a score with no statistical difference compared to FIX-only “on-demand” therapy “FIX” group." (PMID 31892201, 2019). "Therefore, it has been suggested that CRP serum levels and, by extension, disease activity scores containing this APR are not sensitive markers of inflammation (synovitis) in patients treated with anti-IL-6R or JAKi, in contrast to other biological therapies, such as TNF inhibitors." (PMID 35054349, 2022). "Along with our previous data showing that anti‐TNF treatment does not alter pain‐related behavior in DMM‐operated mice 9, these results suggest that synovitis is not the principal driver of pain‐related behavior in these animals." (PMID 26605536, 2016). "Unlike TNF-alpha treated condyles, CFA treated condyles showed significant soft tissue changes, including pannus formation in both the anterior and posterior TMJ disc attachments and synovitis." (PMID 31603905, 2019). "However, severity of stifle synovitis in dogs with CR is not significantly related to serum and synovial fluid CRP, INFγ, and TNFα." (PMID 24892866, 2014).
fungal infections (139 papers, 2005 to 2025). "Th1-associated cytokines, such as IL-1β, IL-2, IFN-γ, and TNF-α, play crucial roles in macrophage recruitment, activation, and the generation of reactive oxygen species to combat fungal infections while promoting CD4+ T-cell responses." (PMID 41425969, 2025). "These TNF antibody treatments carry an increased risk of fungal infection, particularly in those treated for gastrointestinal disease." (PMID 38713531, 2024). "The concomitant use of other immunosuppressants is a well-established factor in increasing the risk of fungal infections in patients taking anti-TNF drugs." (PMID 38238209, 2024). "As early as in the first decade of their use, some reviews drew attention to the association of fungal infections with anti-TNF drugs,43, 44, and in 2008 the FDA warned about the increased risk of invasive fungal infections after 240 cases of histoplasmosis." (PMID 38238209, 2024). "This TNF-α signaling through TLR4 axis in alcoholic hepatitis has been markedly appreciated but anti-TNF-α therapy often associated with hepatotoxicity, and bacterial/fungal infection." (PMID 38146363, 2023). "As with all anti-TNF-a therapies, golimumab increases patients’ risk of upper respiratory tract infections, sinusitis, bronchitis, viral infections, and fungal infections as a result of their systemic immunosuppressive effects." (PMID 37511975, 2023). "After controlling for comorbidities, IBD severity and TPN use, both corticosteroids (HR 5.4, CI 4.6–6.2) and anti-TNF use (HR 1.6, CI 1.3–2.1) were associated with increased risk of invasive fungal infections." (PMID 36911593, 2023). "GM-CSF deficiency impairs the production of TNFα and IFNγ, which are important for the control of intracellular fungal infections." (PMID 36177012, 2022). "The use of TNF inhibitors is accompanied by a potential risk of fungal infection, leading to a black box warning related to potential opportunistic infections." (PMID 35174101, 2021). "Due to the impact on the immune-mediated natural defense, anti-TNF-α, a pro-inflammatory cytokine has been associated with an increased risk of infection, particularly reactivation of latent TB and fungal infections." (PMID 31964419, 2020). "TNF-α stimulates polymorphonuclear neutrophils (PMNs), which in turn increase oxygen radical release and cause enhanced hyphal damage against fungal infections." (PMID 33042859, 2020). "Until now, data on fungal infections associated with TNF-alpha blockade were limited to isolated cases or small number of patients." (PMID 31754120, 2019). "Many studies using different pathogenic models of bacterial, viral and fungal infections have highlighted the importance and requirement of TNF- and NO-producing monocytes as facilitators of the resolution of an infection." (PMID 30349538, 2018). "A major concern of anti-TNF-α treatments is an increased risk of serious bacterial, viral, and fungal infections." (PMID 29184553, 2017). "Increased susceptibility to invasive fungal infections in patients on anti-TNF-α therapies underlines the need for understanding the cellular effects of TNF-α signaling in promoting protective immunity to fungal pathogens." (PMID 27406560, 2016). "Fungal infections associated with TNF-alpha blockade have been reported occasionally, and they are limited to isolated cases or small series of patients." (PMID 25755904, 2015). "Prospective studies are needed to accurately assess the risk of fungal infections during treatment with anti-TNFα." (PMID 25379301, 2013). "They produce cytokines such as TNF and IL-6, both of which play a role in determining susceptibility to fungal infections." (PMID 23675302, 2013). "The risk of development of serious invasive fungal infections in patients on anti-TNF therapy has been increasingly recognized over the past several years." (PMID 21605439, 2011).
fungal infections (continued). "We have not found any Acremonium fungemia reports in association with infliximab, but fungal infections with TNF-α blockers have been well described." (PMID 22567476, 2011). "TNF-α is associated with the immune response to fungal infection, and increased expression has been linked to an augmented capacity of PMNs to damage Aspergillus hyphae, possibly through enhanced oxidative mechanisms, and to increased phagocytic activity against conidia." (PMID 40558956, 2025). "However, in our study corticosteroid exposure was associated with a much greater risk of fungal infection than anti-TNF." (PMID 36911593, 2023). "TNF-α blockers such as infliximab have been linked to an increased risk of infections, especially opportunistic fungal infections, with reported variable incidences of invasive fungal infection ranging from 6% to 50%." (PMID 37509268, 2023). "However, our data are the first to longitudinally describe an association between rapid declines in TNF-α concentrations and impaired clearance of a fungal infection in humans." (PMID 30169607, 2019). "Depletion of TNF-α is known to predispose humans to other invasive fungal infections." (PMID 30169607, 2019). "Thus, better knowledge of how TNF-α regulates immune responses during fungal infections is needed to understand and offset the risks associated with therapies blocking TNF-α signaling." (PMID 27406560, 2016). "Importantly, TNF-α-driven DC1 activation and protective T cell responses identified one mechanism of the increased susceptibility to cryptococcal and other fungal infection in patients undergoing treatments with TNF-α blockade therapies." (PMID 27406560, 2016). "However, more recently it has been recognized that TNF-α blockade significantly increases the risk for invasive fungal infections, including Cryptococcus neoformans infection." (PMID 27406560, 2016). "This critical and protective role that TNF-α orchestrates within innate defense systems against fungal infection is further corroborated by the observations that the use of TNF-α antagonists in clinical practice is associated with an increased incidence of aspergillosis." (PMID 23971044, 2013). "TNF-α blockade is associated with invasive fungal infections." (PMID 22567476, 2011). "However, patients taking TNF-α inhibitors may have increased invasive fungal infection risk, which can be life threatening and lead to need withdrawal of TNF-α inhibitor therapy." (PMID 40371340, 2025). "Thus, administration of anti-TNF-α may introduce a particularly greater risk for newly acquired fungal infections that require generation of protective Th1/Th17 responses for their containment and clearance." (PMID 27406560, 2016). "TNF-α is crucial for the immune response to H. capsulatum, and inhibition of TNF-α can impair the body’s ability to control fungal infections, leading to increased susceptibility to DH." (PMID 40137234, 2025). "IL-1α is a potent pro-inflammatory cytokine that not only activates TNFα signaling but also recruits neutrophils to the site of fungal infection." (PMID 41081505, 2025). "Pathway enrichment analysis revealed common immune pathways, such as IL-17, TNF, and chemokine signaling, shared by both fungal infections." (PMID 40521031, 2025). "Many of these cytokines, such as IFNγ, TNFα, GM-CSF, IL-6, IL-17a, and GRO-α, are associated with protection against fungal infections." (PMID 38469300, 2024). "The production of tumor necrosis factor alpha (TNF-α) by Th1 cells, for example, is essential for granuloma formation in fungal infections." (PMID 39452676, 2024). "We aimed to determine the incidence of fungal infections in IBD patients and examine the risk with tumor necrosis factor-alpha inhibitors (anti-TNF) compared with corticosteroids." (PMID 36911593, 2023).
fungal infections (continued). "It is known that TNF-α and IL-6, as critical inflammatory mediators, can resist fungal infection and promote the infiltration of inflammatory cells to remove pathogens, such as increasing the killing of phagocytosed S. schenckii." (PMID 37141335, 2023). "To further confirm this, we measured the protein level of IFN-γ, IL-17A, and TNF-α under fungi infection in both healthy donors and IBD patients." (PMID 37124046, 2023). "Based on their cytokine secretion and functions during fungal infections, T cells are classified into Th1 (IFNγ, GM-CSF, and TNFα), Th17 (IL-17A/F), Th22 (IL-22), Th2 (IL-4 and IL-13), Th9 (IL-9 and IL-10), Treg (IL-10 and TGFβ), and Tr1 (IL-10)." (PMID 36177012, 2022). "TNF-α is a major regulator in the immune response to fungal infection as it can induce protective Th1 responses against fungal pathogens." (PMID 36558799, 2022). "On the other side, LPS primed MCs showed an increased release of TNF-α upon fungal infection with live Candida albicans, thus suggesting a dual role of LPS in inducing both tolerance and training phenotypes depending on the secondary challenge." (PMID 35251027, 2022). "While RSL3 induced BMDM cell death, inflammation, measured by TNFα release, depended on fungal infection." (PMID 36138043, 2022). "SAEs have been reported including malignant tumors and bacterial, viral, and fungal infections, all related to blockade of the physiological effects of TNF‐α." (PMID 32463599, 2021). "Cryptococcus infection is an opportunistic fungal infection that can occur in patients receiving anti-TNF-α treatment." (PMID 34401295, 2021). "T cells of HDs cultured in the presence of C. albicans produced robust amounts of IFN‐γ, TNF‐α, and IL‐17A, cytokines that are important for immunity to fungal infection." (PMID 32609955, 2020). "In fact, TNF-α is critical to defend against bacterial pathogens infection including Mycobacterium tuberculosis and fungal infections such as Candida albicans, Aspergillus fumigatus and Cryptococcus neoformans." (PMID 33519819, 2020). "In the case of fungal infections, the outcome partly depends on the Th1 protective cellular response, which is principally driven by the proinflammatory cytokines TNF, IFN, IL-6, IL-12, and IL-1." (PMID 31484389, 2019). "The quantification of IL-1β and TNFα in the corneas of the mice with fungal infection was determined by ELISA." (PMID 31285488, 2019). "In general, the CD4+ T cells by secreting the cytokines IFN-γ, TNF-α, and IL-17A determine host resistance to severe fungal infections, such as paracoccidioidomycosis, coccidioidomycosis, aspergillosis and candidiasis." (PMID 29520092, 2018). "Pre-clinical and clinical models have shown that iron supplementation reduces TNFα formation in CKD patients while negatively impacting on the host response in mammalian models of invasive fungal infection." (PMID 30544952, 2018). "Immune reconstitution inflammatory syndrome, IRIS, can present in patients with waning TNF-alpha inhibition and an endemic fungal infection." (PMID 30662827, 2018). "Taken together, this data demonstrate that MCs can respond to fungal infections by tightly interacting with C. albicans hyphae and releasing pro-inflammatory mediators as TNF-α and IL-6." (PMID 30555491, 2018). "Histoplasmosis results to be the most common invasive fungal infection among patients treated with anti-TNF agents." (PMID 28146077, 2017). "Although TNF-α inhibitors exhibit significant clinical efficacy, they have many potential adverse effects, including reactivation of mycobacterial and fungal infection." (PMID 27926504, 2017). "IL-1β and TNF are major pro-inflammatory cytokines that are rapidly released after tissue injury and fungal infection, so we determined their expression levels in the colons of mice challenged with C. albicans and treated with DSS." (PMID 28289440, 2017).
fungal infections (continued). "TNF-α has been shown to be necessary for the development of Th1-mediated immunity and plays a pivotal role in clearing various fungal infections, including C. neoformans infection, in animal models (reference 39 and references therein)." (PMID 27165801, 2016). "Tumor necrosis factor alpha (TNFα) is one of the main pro-inflammatory cytokines produced in response to a broad type of bacterial, viral and fungal infections." (PMID 27351838, 2016). "In light of these considerations, the exact incidence of fungal infections complicating TNF-alpha antagonist therapy remains challenging to estimate." (PMID 25755904, 2015). "Since pro-inflammatory cytokines are the main cytokines produced upon fungal infection, we measured production of IL-6 and TNF-α." (PMID 26431038, 2015). "During fungal infections, various pro-inflammatory cytokines such as TNF, IL-12p70, IL-23 and IL-6, produced by the activated leukocytes, result in the promotion of a sustained Th1 and Th17 response." (PMID 23675302, 2013). "TNF-α is a cytokine that is critical for the successful control of fungal infections and the development of a Th1-dependent response." (PMID 22235359, 2012). "Most of the available clinical information on histoplasmosis in patients receiving anti-TNF agents is based upon case reports and small case series, with the largest report a literature review of fungal infections complicating anti-TNF therapy." (PMID 21605439, 2011). "Tumor necrosis factor (TNF) activates T lymphocytes in response to fungal infections through TNF receptors." (PMID 21059262, 2010). "Recent studies indicate that TNF inhibitors increase the incidence of invasive fungal infections, and that JAK inhibitors may confer an even broader risk due to their cytokine-signaling inhibition." (PMID 41439945, 2025). "TNF-α is a pro-inflammatory cytokine that can activate phagocytic cells (such as macrophages and neutrophils) during fungal infections, promoting inflammation at the infection site and stimulating the production of other cytokines and chemokines, thereby enhancing the anti-fungal immune response." (PMID 40415905, 2025). "In a study of more than 30,000 patients treated with anti-TNF during 2007–2009, 158 patients (0.51%) developed mycoses or mycobacterioses; about half of these infections were fungal, including histoplasmosis, pneumocystosis, cryptococcosis, coccidioidomycosis, and blastomycosis." (PMID 38238209, 2024). "Th17 cells can directly activate the local immune response by secreting cytokines, such as IL-17A and IL-17F, which promote the production of various inflammatory mediators (such as IL-6 and TNF-α), thus increasing the intensity of the inflammatory response against bacterial or fungal infections." (PMID 39794999, 2024). "Our study also found that after fungal infection, Dectin-1 affected the expression levels of phenotype-related factors (TNF-α, INOS, IL-6, IL-12, Arg-1, or IL-10) in M1 and M2-type macrophages through the regulation of MAPK signaling pathways, such as p38, JNK, and ERK." (PMID 39478855, 2024). "In a systemic fungal infection model, immunization of the vaccines drastically prolonged the survival time of the infected mice, inhibited kidney colonization of the fungal pathogens, and attenuated the levels of the kidney inflammatory factor TNF-α." (PMID 37896925, 2023). "Th17 cells play an important role in the host defense against fungal infections, such as candidiasis, by stimulating the production of other cytokines, such as TNF-α, IL-6, and IL-1β, and enhancing the recruitment and activation of neutrophils, which are essential for killing Candida cells." (PMID 38003833, 2023). "Antibodies specific for IFN-α7 and IL-22 were significantly more prevalent in patients with only bacterial infections and patients with mixed bacterial/fungal infections, and antibodies against IFN-α10, IL-17A, and TNF-α were more common in patients with mixed bacterial/fungal infections." (PMID 36752204, 2023).